ADA (adenosine deaminase)
Description:
Catalyzes the hydrolytic deamination of adenosine and 2-deoxyadenosine. Plays an important role in purine metabolism and in adenosine homeostasis. Modulates signaling by extracellular adenosine, and so contributes indirectly to cellular signaling events. Acts as a positive regulator of T-cell coactivation, by binding DPP4. Its interaction with DPP4 regulates lymphocyte-epithelial cell adhesion. Enhances dendritic cell immunogenicity by affecting dendritic cell costimulatory molecule expression and cytokines and chemokines secretion (By similarity). Enhances CD4+ T-cell differentiation and proliferation. Acts as a positive modulator of adenosine receptors ADORA1 and ADORA2A, by enhancing their ligand affinity via conformational change. Stimulates plasminogen activation. Plays a role in male fertility. Plays a protective role in early postimplantation embryonic development (By similarity). Also responsible for the deamination of cordycepin (3'-deoxyadenosine), a fungal natural product that shows antitumor, antibacterial, antifungal, antivirus, and immune regulation properties.
Synonyms: ADA1
Tractability: Small molecule: an approved drug acts on it; a structure with a bound ligand is known; a high-quality ligand is known; it belongs to a druggable protein family. Antibody: UniProt places it where antibodies can reach, with high confidence; its Gene Ontology location is reachable by antibodies, with high confidence; the Human Protein Atlas places it where antibodies can reach. PROTAC: ubiquitination databases record sites on it; its protein half-life has been measured; a small molecule that binds it is known.
Target class: Enzyme; Hydrolase
Chemical probes: PENTOSTATIN
Gene: Protein-coding gene on chromosome 20 (44,584,896 to 44,652,252, reverse strand). Ensembl gene ENSG00000196839.
Subcellular location: Cell membrane; Cell junction; Cytoplasmic vesicle lumen; Cytoplasm; Lysosome
Subcellular location (Human Protein Atlas): Plasma membrane; Cytosol
Pathways (Reactome):
Disease: Defective ADA disrupts (deoxy)adenosine deamination
Drug ADME: Ribavirin ADME
Metabolism: Purine salvage
Gene Ontology:
Molecular function: 2'-deoxyadenosine deaminase activity; adenosine deaminase activity; deaminase activity; protein binding; zinc ion binding
Biological process: adenosine catabolic process; adenosine metabolic process; inosine biosynthetic process; negative regulation of adenosine receptor signaling pathway; purine nucleotide salvage; regulation of cell-cell adhesion mediated by integrin; response to hypoxia; response to purine-containing compound; T cell activation; hypoxanthine salvage; purine-containing compound salvage; regulation of circadian sleep/wake cycle, sleep; xenobiotic metabolic process; AMP catabolic process; AMP salvage; dAMP catabolic process; GMP salvage; purine ribonucleoside monophosphate biosynthetic process
Cellular component: cell surface; external side of plasma membrane; lysosome; membrane; plasma membrane; cytosol; anchoring junction; cytoplasm; cytoplasmic vesicle lumen
Genetic constraint (gnomAD): Loss-of-function variants: 45 observed, 48.74 expected, observed/expected ratio (o/e) 0.92, 90% interval 0.73 to 1.18. The upper end of that interval is the gene's LOEUF score, 1.18, which puts it in group 5 of 6, group 1 being the genes least tolerant of losing a copy. Missense variants: 443 observed, 470.91 expected, observed/expected ratio (o/e) 0.94, 90% interval 0.87 to 1.02. Synonymous variants: 169 observed, 176.38 expected, observed/expected ratio (o/e) 0.96, 90% interval 0.85 to 1.09.
Gene-disease validity (ClinGen):
ClinGen rates the evidence that ADA causes each of these diseases.
severe combined immunodeficiency, autosomal recessive, T cell-negative, B cell-negative, NK cell-negative, due to adenosine deaminase deficiency (autosomal recessive): Definitive.
Homologues: Orthologues: macaque ADA (96% identical), chimpanzee ADA (95% identical), pig ADA (90% identical), rabbit ADA (86% identical), dog ADA (85% identical), guinea pig ADA (82% identical), mouse Ada (81% identical), rat Ada (77% identical), tropical clawed frog ada (69% identical), zebrafish ada (63% identical), tropical clawed frog ada.2 (54% identical), Caenorhabditis elegans adah-1 (38% identical). Paralogues in human: MAPDA (23% identical), ADA2 (21% identical).
Diseases named in the same sentence as ADA in open-access papers:
ADA is named in the same sentence as 508 diseases in open-access papers, as found by Europe PMC text mining. Sharing a sentence is not in itself a finding about the gene and the disease. The quoted sentences say what the papers report.
severe combined immunodeficiency (194 papers, 2002 to 2026). Severe combined immunodeficiency (SCID) comprises a group of rare monogenic primary immunodeficiency disorders characterized by a lack of functional peripheral T lymphocytes resulting in early-onset severe respiratory infections and failure to thrive. "In the 1990s, the landmark cure of adenosine deaminase-deficient severe combined immunodeficiency by transferring the ADA gene into T cells and hematopoietic stem and progenitor cells (HSPCs) via gene therapy in clinics led to an upsurge in gene therapy." (PMID 41141388, 2026). "This is evident from the severe clinical phenotypes of patients lacking either enzyme: ADA1 deficiency causes severe lymphopenia (ADA–severe combined immunodeficiency) as a result of intracellular accumulation of toxic purine metabolites." (PMID 39956283, 2025). "These are features of Omenn syndrome (most commonly due to mutations in RAG1 or RAG2) and more mildly of adenosine deaminase severe combined immunodeficiency (ADA-SCID)." (PMID 41181176, 2025). "The first successful gene therapy, which is considered a milestone achievement, employs ex vivo gene therapy to treat severe combined immunodeficiency (SCID) caused by adenosine deaminase (ADA) deficiency." (PMID 39232780, 2024). "ADA-SCID is a form of SCID (Severe Combined Immunodeficiency) caused by adenosine deaminase (ADA) deficiency." (PMID 39188954, 2024). "Cognitive and neurological difficulties are also specifically noted for some specific conditions, adenosine deaminase-deficient severe combined immunodeficiency (ADA-SCID) for example." (PMID 37781398, 2023). "Metabolic detoxification with enzyme replacement therapy (ERT) promotes immune recovery in patients with adenosine deaminase (ADA)–deficient severe combined immunodeficiency (ADA-SCID)." (PMID 36840835, 2023). "Computational analysis of nsSNPs of the ADA gene in Severe Combined Immunodeficiency, through similar protocols, showed one mutation, while studies on TCGR1 and CCBE1 showed more than 10 mutations." (PMID 37322437, 2023). "Enzyme replacement therapy (ERT) with the form of polyethylene-glycol-modified ADA (PEG-ADA) administration displayed significant clinical improvement in adenosine deaminase-deficient severe combined immunodeficiency (ADA-SCID) patients." (PMID 37051232, 2023). "Adenosine deaminase (ADA) deficiency results in one of the more common forms of autosomal recessive severe combined immunodeficiency (SCID)." (PMID 34654999, 2022). "Unconditioned hematopoietic stem cell transplantation (HSCT) is the recommended treatment for patients with adenosine deaminase (ADA)-deficient severe combined immunodeficiency with an HLA-matched sibling donor (MSD) or family donor (MFD)." (PMID 34654999, 2022). "Human gene therapy is a more recent development spurred by the successful treatment, in September 1990, of a patient in the United States with a gene modified cell therapy for severe combined immunodeficiency (SCID) due to adenosine deaminase deficiency." (PMID 35620726, 2022). "Adenosine deaminase (ADA) deficiency causes severe combined immunodeficiency (SCID), characterized by life-threatening infections from bacteria, viruses, and fungi." (PMID 35887219, 2022). "Adenosine deaminase (ADA) deficiency is one of the most common forms of severe combined immunodeficiency (SCID) that arises through AR inherited mutations in the ADA gene, encoding an enzyme involved in the purine salvage pathway." (PMID 34867986, 2021).
severe combined immunodeficiency (continued). "Two patients with adenosine deaminase (ADA)-deficient severe combined immunodeficiency (ADA-SCID) received stem cell-based gene therapy (SCGT) using GCsapM-ADA retroviral vectors without preconditioning in 2003 and 2004." (PMID 34786435, 2021). "Here, thymic alymphoplasia, immunoglobulin A deficiency, GATA2 deficiency (MonoMac disease) and adenosine deaminase-deficient severe combined immunodeficiency (ADA-SCID) are inherited diseases that have been observed as drivers of secondary PAP." (PMID 33804918, 2021). "In fact, deficiency of ADA which brings about an accumulation of adenosine and deoxyadenosine is the most common cause of severe combined immunodeficiency (SCID)." (PMID 34054547, 2021). "Patient WC27 had severe combined immunodeficiency, a pathogenic variant in one allele of the ADA gene that was detected by ES, and a gain of 596 bp including exon 2 of ADA in the other allele that was detected by CMA." (PMID 31101064, 2019). "Insights from the apoptosis-induced effect of ADA deficiency were obtained from studies regarding severe combined immunodeficiency (SCID) caused by mutations in the ADA1 gene." (PMID 31547393, 2019). "In human, a defect in the ADA gene causes severe combined immunodeficiency (SCID) resulting from metabolites of adenosine exerting cytotoxic effects on lymphocytes." (PMID 31379836, 2019). "Mutations in the ADA gene are among the most common causes for severe combined immunodeficiency (SCID)." (PMID 30441833, 2018). "Deficiency of ADA is the most common cause of severe combined immunodeficiency (SCID) caused by a systemic accumulation of Ado and dAdo, which are cytotoxic particularly for immune systems (see Section 4)." (PMID 29522447, 2018). "Twenty-five years ago, bone marrow cells genetically corrected with a retroviral vector were administered to a child suffering from adenosine deaminase-deficient severe combined immunodeficiency (ADA-SCID)." (PMID 30966479, 2018). "Adenosine deaminase (ADA) deficiency is associated with severe combined immunodeficiency (SCID) underscoring its role in immune regulation." (PMID 28916770, 2017). "Inherited mutations in ADA activity cause severe combined immunodeficiency (SCID) in both human and mice." (PMID 26075284, 2015). "Adenosine deaminase-deficient severe combined immunodeficiency (ADA-SCID) is characterized by impaired T-, B- and NK-cell function." (PMID 26682746, 2015). "ADA–PEG is used to treat severe combined immunodeficiency (SCID) in patients with a deficiency in the ADA protein due to an inherited genetic condition." (PMID 26516849, 2015). "Genetic defects in the adenosine deaminase (ADA) gene are among the most common causes for severe combined immunodeficiency (SCID)." (PMID 22969765, 2012). "Even though subsequent gene therapy attempts were controversial, this area of biomedicine obtained the first signs of success by tackling adenosine deaminase-deficient severe combined immunodeficiency (ADA-SCID)." (PMID 20981357, 2010). "About 20% of the cases of human severe combined immunodeficiency are the result of the child being homozygous for defective genes encoding the enzyme adenosine deaminase." (PMID 19830125, 2009). "The safety and tolerability of elapegademase (elapegademase-lvlr; Revcovi®) a PEGylated recombinant adenosine deaminase (ADA), were demonstrated in two Phase 3 clinical trials in the U.S. and Japan in patients with ADA-deficient severe combined immunodeficiency (ADA-SCID)." (PMID 40140214, 2025).
severe combined immunodeficiency (continued). "Patients with adenosine deaminase 1 deficient severe combined immunodeficiency (ADA-SCID) are initially treated with enzyme replacement therapy (ERT) with polyethylene glycol-modified (PEGylated) ADA while awaiting definitive treatment with hematopoietic stem cell transplant (HSCT) or gene therapy." (PMID 38676811, 2024). "Interest in the intracellular metabolism of purine analogues (adenosine and its derivative) arose after the understanding of the pathophysiology of a specific type of Severe Combined Immunodeficiency (ADA-SCID) found to be the result of an inherited deficiency in adenosine deaminase enzyme 1 (ADA1)." (PMID 36761184, 2023). "In this trial, a retrovirus was used to transport normal adenosine deaminase (ADA) genes to T cells isolated from patients, which were then reinfused into the patient’s body to treat children with ADA-deficient severe combined immunodeficiency disease (ADA-SCID)." (PMID 37884969, 2023). "About twenty years later, a new kind of polymer–protein conjugate named Adagen® (pegademase bovine) was first approved by FDA for enzyme replacement therapy against severe combined immunodeficiency disease (SCID) associated with a deficiency of adenosine deaminase." (PMID 35890416, 2022). "Current treatment for adenosine deaminase (ADA)-deficient severe combined immunodeficiency (SCID) includes enzyme replacement therapy (ERT), allogeneic hematopoietic stem cell transplant (HSCT), or ex vivo corrected autologous hematopoietic stem cell gene therapy." (PMID 35288820, 2022). "In addition, subjects affected by severe combined immunodeficiency (SCID) due to mutations in the ADA gene, showed impairment of both significant osteoblasts and bone formation." (PMID 34361096, 2021). "Autologous HSC transplantation following ex vivo gene therapy employing third-generation lentiviruses is ongoing in a number of clinical trials for Wiskott-Aldrich syndrome, ADA severe combined immunodeficiency (ADA-SCID), X-linked SCID, and chronic granulomatous disease (CGD)." (PMID 32775490, 2020). "Among the 52 patients, 3 (5.8%) were diagnosed with severe combined immunodeficiency (SCID): 1 patient had ADA deficiency, and two patients had DNA ligase IV deficiency (LIG4)." (PMID 41705238, 2026). "Since the first gene therapy experiment in 1990, treating two infants with severe combined immunodeficiency (SCID) due to ADA deficiency, gene therapy has been explored and used for various inherited and acquired diseases." (PMID 40362317, 2025). "Inborn genetic variants of ADA result in a rare and potentially fatal autosomal recessive disorder, adenosine deaminase-deficient severe combined immunodeficiency (ADA-SCID)." (PMID 40140214, 2025). "A majority of affected patients have a near complete loss of ADA function resulting in a profound depletion of T-cells, B-cells, and NK-cells; however about 20% of cases have a less complete deficiency of ADA and can present with delayed onset of combined immunodeficiency (CID)." (PMID 38676811, 2024). "One of the earliest attempts to implement this concept occurred in 1990, when a viral vector was employed to deliver the gene encoding adenosine deaminase (ADA) to the T cells of a four-year-old girl with severe combined immunodeficiency (SCID)." (PMID 39065565, 2024). "Some of these diseases, such as adenosine deaminase-severe combined immunodeficiency (ADA-SCID) and X linked-SCID (SCID-X1), have been successfully treated with viral gene therapy." (PMID 38786024, 2024). "Adenosine deaminase (ADA)–deficient severe combined immunodeficiency (ADA-SCID) is a rare, autosomal recessive, systemic, metabolic condition that is usually fatal if left untreated." (PMID 36840835, 2023). "ADA deficiency causes severe combined immunodeficiency disease (SCID) in humans and demonstrates one of the immunopathological roles of DPP444." (PMID 37573441, 2023).